CRP (C-reactive protein)
Diseases named in the same sentence as CRP in open-access papers (continued):
Sharing a sentence is not in itself a finding about the gene and the disease.
melanoma (continued). "Baseline (pre-treatment) serum CRP was reported to have a potential therapeutic predictive value in melanoma patients treated with the anti-CTLA4 antibody tremelimumab." (PMID 24457057, 2014). "Based on many recent studies, it is now widely accepted that an elevated CRP value is a reliable indicator of poor prognosis for certain malignant tumors including melanoma, non-Hodgkin's lymphoma, colorectal, lung, prostate and ovary." (PMID 22103888, 2011). "The CRP role as a predictor of survival has been shown in multiple myeloma, melanoma, lymphoma, and various ovarian-, renal-, pancreatic-, and gastrointestinal-tumors." (PMID 19341447, 2009). "Lactate dehydrogenase was compared to the acute phase protein C-reactive protein (CRP), which we observed to reflect the course of melanoma metastasis in a previous report." (PMID 15280926, 2004). "Altogether, for first diagnosing AJCC stage IV melanoma, CRP is the superior serum marker when compared to the conventional LDH." (PMID 15280926, 2004). "In vivo, CRP reflects Il-6 secretion supported by high correlation between serum CRP and Il-6 concentrations in melanoma patients." (PMID 15280926, 2004). "In this prospective study, we measured LDH and CRP in the serum of 91 consecutive melanoma patients progressing into AJCC stage IV in comparison to 125 patients staying in AJCC stages I, II or III." (PMID 15280926, 2004). "Comparing distributions of the parameters by median values and quartiles by Mann–Whitney test, LDH was not significantly elevated in patients entering AJCC stage IV melanoma (P=0.785), whereas CRP was (P<0.001)." (PMID 15280926, 2004). "We therefore recommend the routine measurement of CRP in follow-up examinations of melanoma patients, which is a simple and cheap test and provides valuable information." (PMID 15280926, 2004). "Overall response by CRP kinetics in patients with malignant melanoma." (PMID 41055020, 2026). "Additionally, elevated circulating levels of pro-inflammatory cytokines, such as tumor necrosis factor-alpha (TNF-α), interleukin (IL)-6, and C-reactive protein (CRP), have been linked to increased melanoma progression and poorer clinical outcomes." (PMID 40507159, 2025). "Our findings are thus compatible with a specific involvement of monocyte-related mechanisms and not of chronic inflammation in melanoma development, in agreement with a previously reported null association with C-reactive protein." (PMID 38783251, 2024). "One study noted the importance of CRP as a predictor of survival in melanoma." (PMID 38952546, 2024). "There was no causal relationship between C-reactive protein and IL-6 on the risk of malignant melanoma." (PMID 38952546, 2024). "Few studies have been published on CRP as a prognostic marker for progression in melanoma patients." (PMID 36765660, 2023). "Also, another study highlighted CRP combined with the lymphocyte-to-monocyte ratio as a marker for melanoma recurrence in stage III melanoma cases with microscopic sentinel lymph node metastasis." (PMID 37873776, 2023). "Our clinical observations corroborate the recently described prognostic association between plasma IL-6/CRP and poor survival of ICI-treated melanoma patients, and they identify high tumor IL6 expression as a predictor of poor atezolizumab monotherapy outcome in RCC." (PMID 36599350, 2023). "Interestingly, in the present study, not only melanoma but also NSCLC patients responded less well to CPI treatment if pre‐treatment CRP levels are elevated." (PMID 37084178, 2023). "In melanoma where CRP impairs adaptive immunity, a study demonstrated that compared to CRP < 10 mg/L, CRP ≥ 10 mg/L conferred poorer overall survival in subjects with any stage, stage I/II, or stage III/IV disease, and worse disease-free survival for those with stage I/II disease." (PMID 37873776, 2023).
melanoma (continued). "In addition to playing a role in diagnosis, serological markers such as LDH, S100, and C-reactive protein (CRP) also play an important role in the evaluation of melanoma prognosis." (PMID 37427124, 2023). "CRP, an acute-phase protein produced by the liver in response to elevated cytotoxin levels, has already been suggested as a potential biomarker for several cancers including melanoma." (PMID 35494048, 2022). "In multivariate analysis, including tumor type (melanoma vs. other), ECOG (0 vs. other), presence of grade ≥ 3 irAEs, and peripheral blood C-reactive protein (CRP) level (under or ≥10 mg/L), the association between improved PFS and grade ≥ 3 irAEs was retained." (PMID 35565405, 2022). "The levels of serum acute phase reactants including CRP, serum amyloid A and P, and complement components could also contribute significantly to the treatment stratification in melanoma patients." (PMID 33777757, 2021). "Serum IL-6 and CRP may therefore function as prognostic factors in melanoma patients receiving single agent and combination checkpoint inhibition." (PMID 33924623, 2021). "This could provide CRP with a direct immunosuppressive role that might explain the poor survival in melanoma patients with high CRP levels." (PMID 33562331, 2021). "With regard to patients with melanoma, recent data have suggested that CRP might bind to T cells and, thus, suppress their function in the earliest stages of T-cell activation in a dose-dependent manner." (PMID 33562331, 2021). "Hornung first studied the effect of CRP on cultured human melanoma cells." (PMID 34552600, 2021). "One more important limitation of the study is that we evaluated the correlation between antiganglioside antibodies and inflammation markers in melanoma (IL-8 and CRP) only after or between the surgical treatment of melanoma, newer therapies being also in place." (PMID 32855975, 2020). "Besides, several studies have found that the inflammatory markers c-reactive protein (CRP) and alkaline phosphatase (AP) are independent prognostic biomarkers in patients with both early-stage and advanced-stage melanoma." (PMID 32631431, 2020). "Elevated CRP has been correlated with poor prognosis in melanomas." (PMID 33257647, 2020). "Notably, the previously reported composite cytokine signature in melanoma and the composite cytokine signature identified in the current study share several of the same individual cytokines, such as CRP, TIMP-1, and FRTN, but also include different cytokines." (PMID 31829287, 2019). "Materials and methods: During January 2014–May 2015 we determined MIA, LDH and CRP serum concentrations in 100 melanoma patients (22-stage I, 42-stage II, 25-stage III, 13-stage IV) and 51 healthy donors." (PMID 27461275, 2016). "We believe that simultaneous measurement of MIA/CRP best describes melanoma patients." (PMID 27461275, 2016). "Therefore, MALDI-TOF mass spectrometric analysis identifies serum amyloid A as a valuable prognostic marker for all stages of melanoma, with increased specificity and sensitivity for early stages when combined with C reactive protein." (PMID 32309563, 2015). "Galectin-3 concentration was shown to be significantly higher in the group of patients with melanoma compared with healthy volunteers, and galectin-3 concentration significantly correlated with both serum lactate dehydrogenase and C-reactive protein in the melanoma group." (PMID 23658855, 2010). "However, we have examined L-CRP in the serum of patients with advanced melanoma and ovarian cancer, measured serially 1-2 days apart, and identified an apparent 'cycle' in the CRP levels." (PMID 19948067, 2009). "Following excision of the primary melanoma, CRP measurement may contribute to earlier detection of distant metastasis, possibly getting some patients free of disease by surgery or radiation." (PMID 15280926, 2004). "As melanoma cells are known to produce Il-6, serum CRP might reflect Il-6 production from the tumour." (PMID 15280926, 2004).
melanoma (continued). "For instance, a retrospective study of melanoma patients treated with immune checkpoint inhibitors targeting CTLA-4 and PD1 showed that decreased overall survival was associated with elevated baseline levels of IL6, high neutrophil-to-lymphocyte ratio, and elevated C-reactive protein (CRP) levels." (PMID 34202272, 2021). "Patients who experienced no irAE were at the highest risk for melanoma relapse, while, within patients diagnosed with an irAE, those with an elevated CRP (>2xULN) were at higher risk for relapse compared to those diagnosed with an irAE and CRP < 2xULN." (PMID 33925387, 2021). "CRP could play a role as a prognostic serological biomarker in early-stage melanoma patients." (PMID 34199802, 2021). "In cutaneous melanoma, IgM anti-GD1a could be considered a marker associated with melanoma progression based on the negative correlation with CRP and IL-8 as shown in our study." (PMID 32855975, 2020). "In addition, in melanoma elevated levels of CRP may reflect the amount and activity of circulating proinflammatory cytokines, e.g., interleukin 8 (IL-8)." (PMID 32855975, 2020). "Additionally, during the few days after each successive vaccination, a CRP-mediated harmful activity of the innate immune system on melanoma cells could be triggered in micrometastatic deposits." (PMID 30450100, 2018). "For LDH and CRP, ROC-AUC analysis in melanoma patients showed that CRP (AUC = 0.933) was superior to LDH (AUC = 0.491) in discriminating stage IV melanoma." (PMID 40563651, 2025). "Blood tests, including complete blood count (CBC), C-reactive protein (CRP), erythrocyte sedimentation rate (ESR), and human melanoma black 45 (HMB-45) (melanoma marker), were unremarkable." (PMID 41458825, 2025). "Furthermore, high CRP levels have been reported to induce an immunosuppressive environment by inhibiting T‐cell proliferation and downregulating co‐stimulatory molecules on dendric cells (DCs) in melanoma, indicating that CRP blockade is a therapeutic strategy to enhance ICI therapy in cancer." (PMID 39564003, 2024). "Novel serum biomarkers, including LDH, CRP, sPD-L1, and IL-6, and metabolite signatures like NGS hold promise in predicting responses to ICIs in melanoma." (PMID 39282490, 2024). "Nevertheless, the factor with the strongest association with RFS was high CRP, with the combination of high CRP and low LMR having the strongest predictive power for melanoma recurrence in our patient cohort." (PMID 36765660, 2023). "Doing so, we detected that a combined score of high CRP and low LMR was the strongest and most significant prognostic factor for melanoma recurrence when compared to all investigated parameters." (PMID 36765660, 2023). "Compared to the abundantly distributed and unspecific circulating protein CRP and cytosolic enzyme LDH, the cytoplasmic protein S-100B is considered as a more specific and reliable marker for malignant melanoma." (PMID 35494048, 2022). "Measurements included LDH, interleukin (IL)-6, IL-1β, IL-17, C-reactive protein (CRP) and tumor necrosis factor (TNF)-alpha as well as tumor markers S100 and melanoma inhibitory activity (MIA)." (PMID 33837821, 2021). "In melanoma, the baseline level and change in white blood cells (WBCs), lactate dehydrogenase (LDH) and C-reactive protein (CRP) can predict the response and survival of patients treated with anti-PD-1 immunotherapy." (PMID 34218801, 2021). "Elevated pre-treatment CRP level was also shown to be related to poor OS in both anti-PD-1 and anti-CTLA-4 melanoma therapies." (PMID 32992737, 2020). "Several other circulating proteins have shown diagnostic and prognostic value for melanoma, including S100B, C reactive protein (CRP) and melanoma-inhibiting activity (MIA) protein but all have limitations in routine clinical use." (PMID 29343260, 2018). "This study aims to compare the ability of three serum markers, Melanoma Inhibitory Activity (MIA), LDH and C Reactive Protein (CRP), to identify patients with melanoma." (PMID 27461275, 2016).
melanoma (continued). "Unexpectedly, CRP resulted as the more favourite serum marker: This acute phase protein was superior to LDH and contributed significantly in discriminating melanoma patients entering AJCC stage IV from patients staying in AJCC stages I, II or III." (PMID 15280926, 2004). "Next, we compared CRP to the combination of CRP and LDH in the diagnosis of AJCC stage IV melanoma entry." (PMID 15280926, 2004). "In addition, we examined leukocytes and their subsets relevant to melanoma progression (neutrophils, lymphocytes, and the neutrophil-to-lymphocyte ratio (NLR)), as well as the inflammation marker CRP." (PMID 40652269, 2025). "As suggested by our data, higher CRP showed remarkable relation to dismal OS (HR = 2.26, 95% CI = 1.89-2.71, p < 0.001) and inferior PFS (HR = 1.84, 95% CI = 1.13-2.98, p = 0.014) of melanoma patients." (PMID 40539745, 2025). "Altogether, we detected strong associations of NLR, LMR and CRP with RFS, which were independent of other known prognostic parameters in our cohort of stage III melanoma patients with microscopic SLN metastasis." (PMID 36765660, 2023). "Hence, although the biological mechanism remains elusive, CRP depicted good performance for irAE prediction in NSCLC, in consistence to previous findings in melanoma patients." (PMID 35844547, 2022). "In our study, we aimed to explore the relationship between blood biomarkers in melanoma, such as lactate dehydrogenase (LDH), C-reactive protein (CRP) and S-100B, with imaging-based total tumor burden in metastatic melanoma patients treated with immune checkpoint inhibition." (PMID 35494048, 2022). "While CRP did not directly alter the growth curve of such cells, CRP added with lymphocytes not only resulted in no growth of the melanoma cells after 72 hours of culture but resulted in a 75% reduction in viability of the initial inoculum." (PMID 34552600, 2021). "A higher CRP level is the independent negative prognostic biomarker for melanoma patients related to poor OS, compared to patients with normal CRP levels." (PMID 32992737, 2020). "In multivariate analysis of a small study of PD1ab-treated melanoma patients, baseline CRP levels were no independent biomarkers for OS." (PMID 30002656, 2018). "Furthermore, PS, MDT, and CRP at baseline, along with the already established LDH, are potential prognostic markers for advanced melanoma cases." (PMID 27764805, 2016). "For instance, S100B, C reactive protein (CRP), lactate dehydrogenase (LDH), pro-platelet basic protein precursor PPBP and IL-8 may help to determine the prognosis of melanoma patients." (PMID 23533572, 2013). "Describing their distributions by median values and quartiles using the Mann–Whitney test, serum CRP was markedly elevated in patients entering AJCC stage IV melanoma (P<0.001), whereas LDH was not (P=0.785)." (PMID 15280926, 2004). "These include C-reactive protein (CRP), interleukins (IL)-1, -6, and -8, IL-1 receptor antagonist (IL-1Ra), soluble IL-6 receptor (sIL-6R), tumor necrosis factor-alpha (TNF-α), a chemokine promoting macrophage migration, chemokine C-C motif ligand 3 (CCL3), and melanoma inhibitory activity (MIA)." (PMID 34441422, 2021). "In our present study, anti-GM3 negative correlations with IL-8 and CRP are suitable with the hypothesis that patients with primary melanoma with a high level of IgM anti-GM3 have a favourable prognosis." (PMID 32855975, 2020). "In this study, we investigated the clinical and prognostic value of volumetric PET parameters in a patient cohort with advanced melanoma undergoing 18F-FDG-PET/CT by direct correlation with the established serologic tumor markers LDH and S-100 protein and the inflammatory markers AP and CRP." (PMID 32631431, 2020). "CRP is a nonspecific inflammatory parameter which might have a role in the detection of melanoma progression." (PMID 22287956, 2012).
melanoma (continued). "There was a greater proportion in the non-discontinuing group that had stage M1d melanoma and CRP > 2x the ULN compared with the discontinuing group, suggesting that the non-discontinuing group might have had a greater proportion of patients with a poorer prognosis at baseline." (PMID 34771712, 2021). "Preoperative increased CRP levels did not correlate to smoking anamnesis; one out of six melanoma patients with BM (20%) was a smoker and exhibited preoperative CRP levels > 10 mg/L compared to six smokers out of 24 (25%) patients with preoperative CRP levels ≤ 10 mg/L (p = 1.0)." (PMID 33562331, 2021). "Therefore, CRP is not a marker which is exclusively increased in melanoma." (PMID 32631431, 2020). "On the 40th day (6th week) post treatment, sera levels of albumin (g/dL), calcitonin (ρg/ml), CEA (ng/ml), CRP (mg/ml), or LDH (U/L) in melanoma mice were not significantly different between treatment groups and control groups (data not shown)." (PMID 30611221, 2019). "Altogether, LDH did not discriminate melanoma patients entering AJCC stage IV from patients staying in AJCC stages I, II or III in follow-up examinations, whereas CRP did upon ROC-AUC analysis." (PMID 15280926, 2004).